PAX8 (paired box 8)
Diseases named in the same sentence as PAX8 in open-access papers (continued):
Sharing a sentence is not in itself a finding about the gene and the disease.
cervical cancer (11 papers, 2013 to 2025). A primary or metastatic malignant neoplasm involving the cervix. "Inheritance of PAX8 genomic mutations has been previously associated with cervical cancer by our team." (PMID 40065506, 2025). "A meta-analysis of GWAS identified several candidate genes most likely associated with cervical cancer predisposition, including PAX8/PAX8-AS1, LINC00339, CDC42, CLPTM1L, HLA-DRB1, and GSDMB." (PMID 39595021, 2024). "Our results provide new evidence for the genetic susceptibility to cervical cancer, specifically the PAX8, CLPTM1L, and HLA genes, suggesting disruption in apoptotic and immune function pathways." (PMID 33794208, 2021). "One notable finding from our cervical cancer GWAS was rs10175462 in PAX8 on 2q13, which, to our knowledge, is the first genome-wide significant cervical cancer risk SNP identified outside of the HLA region in a European ancestry population." (PMID 32887889, 2020). "A recent GWAS has confirmed the importance of HLA genes for the genetic susceptibility to cervical cancer, along with new risk variants in the PAX8 and CLPTM1L genes, suggesting a disruption in apoptotic and immune function pathways plays a key role in the susceptibility to HPV-associated cancers." (PMID 34683414, 2021). "In a candidate SNP study of PAX8 eQTLs in a Han Chinese population, two variants in LD with rs10175462 in Europeans (rs1110839, r2 = 0.33; rs4848320, r2 = 0.34) were suggestively associated with cervical cancer risk in the same direction." (PMID 32887889, 2020). "A case report noted that PAX8 immunostaining was valuable in diagnosing metastatic cervical cancer of the breast." (PMID 34540435, 2021). "We identified novel variants in PAX8 and CLPTM1L intronic regions in UK Biobank samples, which were replicated in the FinnGen dataset of cervical cancer phenotypes." (PMID 33794208, 2021). "Three SNPs were replicated in the independent Finnish dataset of 1648 invasive cervical cancer cases: PAX8 (rs10175462; p=0·015), CLPTM1L (rs27069; p=2·54 × 10−7), and HLA-DQA1 (rs9272050; p=7·90 × 10−8)." (PMID 33794208, 2021). "Replication was achieved for the PAX8 SNP rs10175462 (and indel rs35724515) for invasive cervical cancer (p=0·015) and cervical dysplasia (p=0·0002) phenotypes with concordant direction of effect." (PMID 33794208, 2021). "PAX8 is a strictly regulated transcription factor that has also shown increased immunostaining in cervical carcinomas." (PMID 34540435, 2021). "Instead, numerous previously unreported PAX8 aberrant transcripts were found in both cervical carcinoma-derived cell lines and tumor samples." (PMID 34540435, 2021). "PAX8 polymorphisms have been suggested as risk factors of childhood acute lymphoblastic leukemia (ALL) and non-Hodgkin lymphoma, whilst the expression of specific alleles is associated with a decreased risk of developing cervical cancer." (PMID 36831395, 2023). "Three of these SNPs, PAX8 (rs10175462), CLPTM1L (rs27069) and HLA-DQA1 (rs9272050) were replicated in the independent Finnish dataset of 1648 invasive cervical cancer cases." (PMID 34683414, 2021). "In a recent study, RNA analysis in cervical samples uncovered upregulation of PAX8 transcripts in HPV-positive lesions, presumed to be the main culprit behind cervical carcinoma." (PMID 34540435, 2021). "Although several specimens expressed PAX8 immunostaining in cervical cancer samples in several studies, they were not highly specific." (PMID 34540435, 2021). "We were able to replicate three SNPs in PAX8 (rs10175462), CLPTM1L (rs27069), and HLA-DQA1 (rs9272050) in an independent Finnish dataset of 4246 cervical dysplasia cases, 298 CIN3 cases, and 1648 cervical cancer cases (FinnGen)." (PMID 33794208, 2021). "Although the PAX8 gene gives rise to four isoforms through alternative messenger ribonucleic acid (mRNA) splicing, there is no available data that can determine which PAX8 isoform is present in cervical tissues and cervical carcinoma." (PMID 34540435, 2021).
cervical cancer (continued). "Hence, PAX8 immunostaining can play an essential role as an adjunct tool in diagnosing cervical cancer, but a negative result cannot rule out the diagnosis." (PMID 34540435, 2021).
endometrioid carcinoma (11 papers, 2015 to 2025). "Therefore, perinuclear dot-like staining of cytokeratin and EMA, loss of expression of PAX-8, ER, PR, and E-cadherin would be helpful to distinguish UC from conventional endometrioid adenocarcinoma." (PMID 28069049, 2017). "Based on the tumor's extensive tubular growth pattern and the possibility of PAX8 negativity in endometrioid carcinoma, the final diagnosis favored endometrioid carcinoma." (PMID 40959354, 2025). "Despite the absence of hallmark mutations and typical immunomarkers such as PAX8 and CK7, the overall architecture, clinical setting, and subtle histologic cues support a diagnosis of endometrioid carcinoma of the fallopian tube." (PMID 40959354, 2025). "PAX8 is highly expressed in endometrioid adenocarcinomas, uterine serous carcinomas, and endometrial clear cell carcinomas." (PMID 33504059, 2021). "Notably, PAX8 negativity can occur in endometrioid carcinoma involving adnexal tissue with low-grade morphology, as seen in this case." (PMID 40959354, 2025). "On the other hand, in 5 (42%) of the 12 cysts derived from three iPAD mice, cells on some parts of the Pax8-positive epithelium showed markedly stratified proliferation and abnormal structures, such as back-to-back and cribriform patterns, corresponding to endometrioid carcinoma." (PMID 37221199, 2023). "In addition, PAX8 is overexpressed in serous uterine carcinoma compared to endometrioid adenocarcinoma." (PMID 26132201, 2015). "The endometrioid carcinoma presented groups of atypical cells located in the upper dermis, which expressed CTK AE1/AE3 and PAX8." (PMID 40407482, 2025). "This case underscores the importance of recognizing that endometrioid carcinoma can masquerade as FATPWO and that loss of PAX8 and CK7 does not preclude a diagnosis of endometrioid carcinoma in the adnexal region." (PMID 40959354, 2025). "While endometrioid carcinoma commonly shows diffuse and strong PAX8 positivity, primary MOC is often negative or only weakly positive for this marker." (PMID 39040449, 2024). "Overall, therefore a cytokeratin/EMA-focal and PAX8/ER/E-cadherin-negative immunoprofile, along with loss of BRG-1 or INI-1 expression would favor undifferentiated or dedifferentiated carcinoma over grade 3 endometrioid carcinoma." (PMID 30550483, 2019). "However, unlike FATWO, endometrioid carcinomas present with squamous morules, glandular cells with luminal polarization, and intraluminal mucin that predominantly involve the fallopian tube and show positive immunoreaction with PAX-8, EMA, ER, and PR." (PMID 40034930, 2024). "Alterations in the immunohistochemical characteristics of ER, PTEN, PAX8, and PAX2 were noted in PDXs and their passages regardless of the parental tumor phenotypes, i.e., endometrioid carcinomas and carcinosarcomas." (PMID 37231035, 2023). "Borderline seromucinous tumors and endometrioid carcinoma with mucinous differentiation are usually positive for IHC stains CK7, ER, PR and CA125 as well as PAX8 and are usually negative for CK20, CDX2 and WT1." (PMID 33736662, 2021). "In 3 out of the 6 OEM from iPAD mice, Pax8-positive cells in OEM partially lacked the expression of both Pten and Arid1a and showed cellular stratification, a cribriform structure, and stromal invasion with prominent nuclear atypia, corresponding to endometrioid carcinoma." (PMID 37221199, 2023).
anaplastic carcinoma (10 papers, 2007 to 2026). "Immunohistochemically, undifferentiated carcinomas and the undifferentiated component of dedifferentiated carcinomas often show loss of PAX8, E-cadherin, ER, and PR immunoreactivity 121,130." (PMID 30550483, 2019). "The undifferentiated carcinoma component was variably positive for PAX-8, cytokeratin, EMA, estrogen receptor, and neuroendocrine markers." (PMID 29545232, 2018). "The majority of undifferentiated carcinomas (and the undifferentiated component of dedifferentiated carcinoma) lack expression of PAX8, ER, and PR but up to 20% of tumors may show focal staining with these markers 121,130." (PMID 30550483, 2019).
melanoma (10 papers, 2020 to 2024). A malignant, usually aggressive tumor composed of atypical, neoplastic melanocytes. "As a comparison we investigated PAX gene expression in the melanoma cell line UACC62 which had only PAX8 expression (0.04-fold), and the prostate cancer cell line PC-3 which expressed PAX6 at 5-fold and PAX5 and PAX8 at the same level as housekeepers (1-fold)." (PMID 34722257, 2021). "All but ESR1, PAX8, PGR, TMEFF2, were associated with prognosis of breast, cervical, colorectal, head and neck, liver, lung, melanoma, ovarian, pancreatic, renal, or urothelial cancers." (PMID 34680205, 2021). "In a study of 263 melanomas, the expression of PAX8 was reported in 7.9% of cases and was significantly associated with spindle cytomorphology." (PMID 34449584, 2021). "The PAX8 CREAG is mutated in other cancer types, but this only reached statistical significance in melanoma, kidney, and OCs." (PMID 32332753, 2020). "In some instances, cells depended strongly on the lineage factor, for example PAX8 in RCC, MITF in melanoma, and IRF4 in multiple myeloma (MM)." (PMID 37554444, 2023). "Immunohistochemically, tumor cells were positive for cytokeratin and vimentin, but negative for cytokeratin 7 (CK 7), thyroid transcription factor-1 (TTF-1), carbonic anhydrase-9 (CA-9), paired box gene 8 (PAX8), leukocyte common antigen (LCA), and human melanoma black 45 (HMB45)." (PMID 33950950, 2021). "All other markers tested were negative (pan-melanoma, HMB45, Melan A, keratin AE1/AE3, desmin, alpha smooth muscle actin, h-caldesmon, CD34, p16, CD117, DOG1, myogenin, CD10, estrogen receptor (ER), progesterone receptor (PR), PAX8, WT1, synaptophysin, chromogranin A, CD99 and PRAME))." (PMID 39196362, 2024).
mucinous tumors (10 papers, 2019 to 2026). "For instance, immunohistochemical markers like CK7, CK20, Villin, CDX-2, MUC-2, and PAX8 are employed for the differential diagnosis of ovarian primary mucinous neoplasms (OPMN) and ovarian secondary peritoneal pseudomyxoma." (PMID 40486880, 2025). "Recently, new Müllerian markers (PAX2 and PAX8) are reported as useful markers to differentiate Müllerian mucinous tumors from non- Müllerian tumors." (PMID 35387670, 2022). "With respect to other EOC histotypes, PAX8 is expressed at higher levels in clear cells and endometrioid tumours and at lower levels in mucinous tumours." (PMID 33830648, 2021). "ER, PR, paired box 8 (PAX8), vimentin, and CA125 positivity support OEC, whereas mucinous tumors show opposite staining profiles." (PMID 41425725, 2025). "Most mucinous tumors expressed relatively low mRNA levels of ciliated cell markers FOXJ1 and CAPS and there was a clear dichotomy in PAX8 mRNA expression when mucinous EOC were compared to serous, endometrioid, and clear cell EOC." (PMID 36552773, 2022). "Of note, mucinous tumors expressed low levels of both ciliated cell (FOXJ1, CAPS) and secretory cell (PAX8) cell markers, possibly suggesting a different cell of origin for this histologic subtype." (PMID 36552773, 2022). "Moreover, PAX-8 was strongly expressed in OSMC, which was different from mucinous tumors but similar to serous tumors." (PMID 36670456, 2023). "Therefore, adding PAX8 and SATB2 to the panel of immunostains for differentiating mucinous tumors will be of great benefit." (PMID 31771640, 2019). "For example, OCMs 61 and 72, the two mucinous tumours, were PAX8 negative in both contexts." (PMID 32054838, 2020). "Mucinous tumors and BTs tend to be negative for PAX-2 and PAX-8, two highly sensitive mullerian epithelial markers that are often positive in other ovarian epithelial neoplasms." (PMID 36810485, 2023).
pancreatic cancer (10 papers, 2013 to 2024). "Another study indicated that LINC00958 accelerated tumor initiation in pancreatic cancer by downregulating miRNA-330-5p but upregulating PAX8." (PMID 34672237, 2021). "For example, LINC00958 deletion prevented tumor initiation by sponging the miRNA-330-5p to regulate PAX8 expression in pancreatic cancer." (PMID 32127947, 2020). "The 5 patients showing PAX8-/Calretinin- phenotype represented 2 metastatic breast, 1 colon, 1 gastric, and 1 pancreatic cancer." (PMID 23958394, 2013). "Thus, the MACC1-AS1/PAX8/NOTCH1 axis has been suggested as a putative target for the treatment of pancreatic cancer." (PMID 34827663, 2021). "In addition, the expression of PAX8 is increased in pancreatic cancer tissues in correlation with levels of MACC1-AS1 and the prognosis of patients with pancreatic cancer." (PMID 34827663, 2021).
renal tumors (10 papers, 2021 to 2025). "The study reinforces the importance of using a multidisciplinary diagnostic approach, and the application of markers such as TFE3, PAX8, and CA IX helps confirm the diagnosis and also delineates it from other renal tumors." (PMID 39851801, 2025). "The renal tumors, including the skull and liver metastases, showed immunoexpression PAX8, CK8-18, and cathepsin-K, and negativity for vimentin." (PMID 37938323, 2023). "We found morphological and immunohistochemical features (PAX8, cytokeratin 8–18, cathepsin-K clone 3F9 positivity, and vimentin negativity) overlapping with those observed in the primary renal tumors." (PMID 37938323, 2023). "Transcription factor PAX8, expressed during embryonic kidney development, has been previously detected in various kidney tumors." (PMID 36140438, 2022). "It is useful in differentiating clear cell RCC (ccRCC) from ovarian clear cell carcinoma, as PAX8 would be positive in both tumors, whereas RCCm would be positive only in the renal neoplasm." (PMID 36428491, 2022). "While the ASPSCR1-TFE3 fusion model resulted in extrarenal PEComas26, PAX8 was widely expressed in the renal tumors in this model, suggesting that these are best classified as tRCC, though quantification of PAX8 levels relative to normal kidney was not performed." (PMID 41044182, 2025). "For example, PAX8, which is a useful marker for renal neoplasms, is only rarely positive in ACC." (PMID 39129823, 2024). "However, caution should be taken with the use of PAX-8 because it can be expressed in both thyroid and renal neoplasms as well as other tumors gynecologic origin." (PMID 37990226, 2023). "PAX2 and PAX8 markers might helpful in diagnosis of Wilms tumor and may differentiate it from other histologically similar kidney tumors." (PMID 34306127, 2021). "Among kidney tumors with TFE3 gene translocations, most are morphologically heterogeneous carcinomas positive for the immunohistochemical nuclear tubular marker PAX8." (PMID 39410016, 2024). "A few studies examined its expression in renal tumors, but for the first time here we present PAX8 expression in non-tumor kidney diseases including those with chronic course, as well as cases of acute kidney injury." (PMID 36140438, 2022).
urothelial carcinoma (10 papers, 2013 to 2026). A malignant neoplasm derived from the transitional epithelium of the urinary tract (urinary bladder, ureter, urethra, or renal pelvis). "The immunohistochemical (IHC) profile showed positivity for cytokeratin (CK) and carcinoembryonic antigen (CEA), with negativity for markers typically associated with RCC (e.g., PAX8, CD10) and urothelial carcinoma (e.g., GATA3, uroplakin)." (PMID 40351999, 2025). "In addition, positive PAX8 expression was detected in 52% and 67% of primary and metastatic nested urothelial carcinoma, respectively." (PMID 37627900, 2023). "A significant proportion of nested urothelial carcinoma cases express PAX8." (PMID 37627900, 2023). "Therefore, PAX8+/p63- strongly favors CDC, while PAX8-/p63+ favors urothelial carcinoma." (PMID 38957193, 2023). "Paired-box gene 8 (PAX8) and p63 have emerged as important IHC markers in that effort with CDC showing positivity for PAX8, while p63 is positive in urothelial carcinoma cases." (PMID 38957193, 2023). "Positive immunoreaction for HNF and PAX8 (or PAX2) helps exclude non-CCA types of urothelial carcinoma." (PMID 24455377, 2013). "Notably, markers typically associated with RCC (PAX8, CD10) and urothelial carcinoma (GATA3, uroplakin) were negative, supporting a diagnosis of primary adenocarcinoma." (PMID 40351999, 2025). "Other positive stains include PAX8 and Mucin, and these can help differentiate CDC from urothelial carcinoma, as these stainings are usually negative in urothelial carcinoma." (PMID 34277493, 2021).
kidney cancer (9 papers, 2016 to 2025). Primary or metastatic malignant neoplasm involving the kidney. "To illustrate this functionality, we applied it to a specific use case for PAX8, a transcription factor frequently dysregulated in kidney cancer." (PMID 40608961, 2025). "Recently, it was shown that MECOM interacts with PAX8, a transcription factor that is an oncogene for ovarian and kidney cancers and can serve as an indicator of PAX8 transcriptional activity." (PMID 35581546, 2022). "In order to characterize the transcriptional program imposed by PAX8 in kidney cancer cells, we sought to quantify gene expression changes by RNA-seq upon PAX8 knockdown across multiple RCC models." (PMID 31431624, 2019). "In summary, CRC analysis combined with genome-scale genetic screens identify PAX8 as a candidate oncogenic factor in kidney cancer cells." (PMID 31431624, 2019). "In order to identify the subset of genes directly controlled by PAX8, we sought to characterize the genome wide occupancy of PAX8 across the same panel of kidney cancer cells." (PMID 31431624, 2019). "Interestingly, HNF1B and PAX8 were both highly expressed and sufficient to impact proliferation/survival of kidney cancer cell lines, making them prime candidates for downstream analyses." (PMID 31431624, 2019). "For example, tissue-specific markers such as NKX3.1, prostate-specific acid phosphatase (PSAP), and androgen receptor (AR) (prostate cancer markers) or PAX8 (kidney cancer marker) could be used to confirm the origin of the detected tumor cells." (PMID 27634877, 2016). "It was previoulsy shown that PAX8 downregulation resulted in increased L1-CAM expression and enhanced migration of kidney cancer cells." (PMID 29435133, 2018). "PAX8 belongs to PAX gene family, which is an important transcription factor in renal organogenesis and a reliable marker for primary kidney cancer." (PMID 28449664, 2017). "All primary cultures showed kidney cancer markers such as CA9, Pax8, CD10 or MIF1a." (PMID 36975533, 2023).